PRRG2 (proline rich and Gla domain 2)
Description:
Vitamin K-dependent protein that is essential for calcium homeostasis and haemostasis.
Synonyms: PRGP2
Tractability: Small molecule: a structure with a bound ligand is known. Antibody: UniProt places it where antibodies can reach, with high confidence; its Gene Ontology location is reachable by antibodies, with high confidence; UniProt predicts a signal peptide or a membrane-spanning region.
Gene: Protein-coding gene on chromosome 19 (49,580,646 to 49,591,004, forward strand). Ensembl gene ENSG00000126460.
Subcellular location: Cell membrane
Subcellular location (Human Protein Atlas): Nucleoli; Nucleoplasm; Cytosol
Gene Ontology:
Molecular function: protein binding; serine-type endopeptidase activity; calcium ion binding
Biological process: blood coagulation; proteolysis
Cellular component: plasma membrane; extracellular region
Genetic constraint (gnomAD): Loss-of-function variants: 23 observed, 25.19 expected, observed/expected ratio (o/e) 0.91, 90% interval 0.66 to 1.29. The upper end of that interval is the gene's LOEUF score, 1.29, which puts it in group 5 of 6, group 1 being the genes least tolerant of losing a copy. Missense variants: 276 observed, 234.1 expected, observed/expected ratio (o/e) 1.18, 90% interval 1.07 to 1.3. Synonymous variants: 104 observed, 94.34 expected, observed/expected ratio (o/e) 1.1, 90% interval 0.94 to 1.3.
Homologues: Orthologues: chimpanzee PRRG2 (98% identical), macaque PRRG2 (93% identical), dog PRRG2 (80% identical), rat Prrg2 (79% identical), mouse Prrg2 (79% identical), pig PRRG2 (76% identical), guinea pig PRRG2 (74% identical), zebrafish c1r (18% identical), zebrafish c1s.1 (13% identical). Paralogues in human: MASP1 (25% identical), MASP2 (25% identical).
Diseases named in the same sentence as PRRG2 in open-access papers:
PRRG2 is named in the same sentence as 10 diseases in open-access papers, as found by Europe PMC text mining. Sharing a sentence is not in itself a finding about the gene and the disease. The quoted sentences say what the papers report.
kidney cancer (1 paper, 2024). Primary or metastatic malignant neoplasm involving the kidney. "Moreover, when juxtaposed with normal renal epithelial cells HK-2, PRRG2 expression exhibits a similar downregulation in the majority of kidney cancer cell lines." (PMID 38227081, 2024).
lung carcinoma (1 paper, 2024). "To this end, we monitored YAP1 phosphorylation in control or PRRG2 stably expressing lung cancer cells." (PMID 38355937, 2024). "In addition to the correlation with OS, we found that high expression of SET or low expression of PRRG2 was also correlated very well with reduced disease-free survival (DFS) of lung cancer." (PMID 38355937, 2024). "Since MMP9 and PRRG2 are key downstream targets of ZBTB11 and/or SET in regulating the metastasis of lung cancer cells, we also considered them in the clinical survival analyses." (PMID 38355937, 2024). "To this end, we first confirmed the interaction between PRRG2 and YAP1 in lung cancer cells." (PMID 38355937, 2024). "However, the expression ectopic PRRG2 profoundly inhibited cell migration and invasion, suggesting that the upregulation of PPRG2 has an antimetastatic effect on lung cancer cells." (PMID 38355937, 2024).
renal carcinoma (1 paper, 2024). A carcinoma arising from the epithelium of the renal parenchyma or the renal pelvis. "This revelation was further corroborated in cell lines from kidney carcinoma, where the majority of kidney carcinoma cell lines exhibited significantly reduced PRRG2 mRNA levels as compared to HK-2." (PMID 38227081, 2024). "Thirdly, we did not investigate the diagnostic and prognostic value of PRRG2 in other renal cancers in this study." (PMID 38227081, 2024).
renal cell carcinoma (1 paper, 2024). "Our revelations denote a substantial correlation between PRRG2 expression and diverse clinical pathological indicators in renal cell carcinoma, alongside a significant association with OS and DFS, particularly in relation to tumor-infiltrating immune cells." (PMID 38227081, 2024).
cancer (3 papers, 2016 to 2024). A tumor composed of atypical neoplastic, often pleomorphic cells that invade other tissues. "We next attempted to investigate the potential mechanisms by which PRRG2 represses cancer cell metastatic behaviors." (PMID 38355937, 2024). "Overexpression of the YAP1-S127A mutant readily reversed the suppressive effect on cancer cell migration induced by PRRG2 overexpression or ZBTB11 knockdown." (PMID 38355937, 2024). "More importantly, the PRRG2 overexpression-mediated reduction in cancer cell migration and invasion was profoundly abolished upon concomitant silencing of YAP1, supporting a critical role of YAP1 in PRRG2-mediated metastatic regulation." (PMID 38355937, 2024). "We scrutinized PRRG2 expression in 36 carcinomas and observed a significant decrease in expression in KIRC as compared to normal tissues." (PMID 38227081, 2024). "Since YAP1 interacted with PRRG2 and was largely required for PRRG2-mediated repression of cancer cell migration and invasion, we mechanistically speculated that PRRG2 likely exerts its metastatic suppressive actions by inhibiting YAP1 activity." (PMID 38355937, 2024). "In the cytoplasmic domain, PRRG2 may possess SH3 and WW binding motifs, whose interactions regulated by WW domains are implicated in several diseases, including cancer and neurological disorders." (PMID 38227081, 2024). "This study aims to explore the prognostic significance of Proline-rich γ-carboxyglutamic acid protein 2 (PRRG2) in Kidney Renal Clear Cell Carcinoma (KIRC), a prevalent and deadly cancer, and its association with immune cell infiltration, a key strategy in developing effective biomarkers." (PMID 38227081, 2024). "Moreover, both the repression of Mmp9 and the activation of Prrg2 were easily recapitulated in Zbtb11 KO MEFs, further confirming our previous results in cancer cells where MMP9 and PRRG2 are critical downstream targets of ZBTB11." (PMID 38355937, 2024).
tumor (2 papers, 2024). "Following the adjustment for tumor purity, the expression of PRRG2 in several immune cells in KIRC was inextricably linked with an array of immunological markers." (PMID 38227081, 2024). "Firstly, although we have investigated the correlation between PRRG2 and immune infiltration in KIRC patients, the molecular mechanisms and roles of PRRG2 in tumor growth, metastasis, and immune evasion require further study." (PMID 38227081, 2024). "We observed that PRRG2 overexpression indeed suppressed tumor cell metastasis." (PMID 38355937, 2024). "Notably, overexpression of PRRG2 or depletion of YAP1 markedly attenuated ectopic ZBTB11-induced tumor metastasis." (PMID 38355937, 2024). "The results evinced that tumor tissues had substantially reduced levels of PRRG2 mRNA expression." (PMID 38227081, 2024). "To assess the role of PRRG2 in vivo, we established a xenograft tumor model to evaluate whether PRRG2 contributes to ZBTB11-mediated regulation of tumor metastasis." (PMID 38355937, 2024). "In addition, overexpression of the YAP1-S127A mutant significantly abolished PRRG2-mediated inhibition of tumor metastasis." (PMID 38355937, 2024). "However, the exact role of PRRG2 in the tumor immune microenvironment requires further exploration." (PMID 38227081, 2024). "Consequently, we posit that PRRG2 could potentially impede tumor proliferation and metastasis through the activation of the Hippo signaling cascade, thereby inhibiting YAP1 activity." (PMID 38227081, 2024). "To gain further insights into the impact of PRRG2 on the tumor microenvironment (TME), we employed CiberSort to examine the relationship between PRRG2 and immune infiltration." (PMID 38227081, 2024). "Crucially, PRRG2 exhibits significant correlations with a spectrum of immune cell markers in KIRC, which in turn modulate tumor cell dynamics and the TME, thereby impacting the survival duration of KIRC patients." (PMID 38227081, 2024). "Furthermore, a significantly lower expression of PRRG2 was observed in KIRC patients in relation to age, tumor stage grade, and patient ethnicity." (PMID 38227081, 2024). "Taken together, our data indicate PRRG2 as a direct target of ZBTB11, which contributes to ZBTB11-, but not SET-, mediated regulation of tumor metastasis." (PMID 38355937, 2024).
PRRG2 also shares sentences with these, for which no sentence is quoted: acute myocardial infarction (1 paper); conjunctivitis (1); diabetes (1); Hypomagnesemia (1).